HCN1 (hyperpolarization activated cyclic nucleotide gated potassium channel 1)
Diseases named in the same sentence as HCN1 in open-access papers (continued):
Sharing a sentence is not in itself a finding about the gene and the disease.
Anxiety (continued). "In mice with chronic stress, the HCN1 channel in the basolateral amygdaloid nucleus has been shown to be an important part of the pathophysiology of anxiety and a potential target for new therapies for anxiety." (PMID 35372451, 2022). "Far less certain, however, is whether the activation of HCN1 by 8-Br-cAMP reduced the positive time significantly in the FST even though more severe anxiety symptoms and weakened exploration ability were detected." (PMID 32198387, 2020). "Additionally, HCN1-related BDNF played a crucial role in the pathogenesis of anxiety were explored in our previous study which found there was a negative correlation between the level of BDNF and HCN1 in the brain." (PMID 29896126, 2018). "Because BDNF and HCN1 play a key role in ethanol withdrawal-induced anxiety, we performed a western blot analysis of BDNF and HCN1 in the Hip and NAc." (PMID 29896126, 2018). "This study suggest that SIRT3 may ameliorate anesthesia/surgery-induced anxiety-like behavior by preventing SOD2 acetylation-mediated mitochondrial oxidative stress and HCN1 channel dysfunction in the mPFC of mice." (PMID 35372451, 2022). "Third, the electrophysiological mechanism of the HCN1 ion channel in anesthesia/surgery-induced anxiety behavior was not explored, which should be studied in further studies." (PMID 35372451, 2022). "Our results suggest that SIRT3 may achieve antianxiety effects through regulation of SOD2 acetylation-mediated oxidative stress and HCN1 channels in the mPFC, further strengthening the therapeutic potential of targeting SIRT3 for anesthesia/surgery-induced anxiety-like behavior." (PMID 35372451, 2022).
Cognitive impairment (7 papers, 2019 to 2024). Abnormal cognition is characterized by deficits in thinking, reasoning, or remembering. "DEEs are characterized by the presence of significant comorbidities, including developmental delay and cognitive impairments; and patients carrying the HCN1 p.G391D and p.M153I variants were reported to display severe and mild intellectual disability, respectively." (PMID 35972069, 2022). "Factors that interfere with this process and alter HCN1 activity may have long‐lasting deleterious effects that lead to network dysfunction underlying cognitive impairment observed in several brain pathologies." (PMID 32329240, 2020). "Another study revealed the importance of deregulation of hyperpolarization-activated cyclic-nucleotide-gated channel 1 (HCN1, a neurofibromin-interacting protein) in the pathophysiology of NF1-associated cognitive deficits." (PMID 34576341, 2021). "Therefore, an age-related decrease of HCN1 and HCN2 protein expression in the aged hippocampus might be related to age-dependent cognitive impairment, alterations of long-term potentiation, and synaptic transmission." (PMID 32128096, 2019).
breast carcinoma (6 papers, 2009 to 2025). "HCN1 is adjacent to other genes that may be related to breast cancer risk including FGF10 and MRPS30, and is just outside a region linked to mammographic density." (PMID 19232126, 2009). "Polymorphisms in or near TOX3, LSP1, HCN1, MAP3K1 and at 2q35 are less strongly associated with breast cancer risk than polymorphisms in FGFR2; the increased risks range from 4% to 20% with each risk allele." (PMID 19232126, 2009). "The polymorphism rs10941679 near HCN1/MRPS30 was also associated with percent dense area; women who were homozygous for the G allele (previously associated with increased breast cancer risk) had 4% to 5% lower densities than women with at least one A allele." (PMID 19232126, 2009). "For SNP rs981782 in the HCN1 gene, the genotype “G/T” increased clinical stage (UICC) III and IV breast cancer risk by1.83-fold (OR = 1.83; 95% CI, 1.20-2.80; p = 0.063) in the codominant model and “G/T-G/G” genotype in the dominant model (OR = 1.62; 95% CI, 1.08-2.45; p = 0.019)." (PMID 27863437, 2016). "In the present study, we demonstrated that genetic variants of the host, such as SNPs of MAP3K1, CYP2B6, UGT1A1, HCN1, ABCB1, and ALDH3A1, may worse the prognosis of HR-positive breast cancer patients, predominantly for premenopausal women." (PMID 28178648, 2017). "On the other hand, some reports suggest that variation in FGFR2, TOX3, HCN1, and at 2q35 may be more strongly associated with estrogen receptor-positive cancers, but mammographic density has not been found to be differentially related to breast cancers by steroid receptor status." (PMID 19232126, 2009). "Genome-wide association studies (GWAS) have identified breast cancer susceptibility loci in or near genes such as FGFR2, TOX3 (formerly known as TNRC9), LSP1, HCN1/MRPS30, MAP3K1 and at 2q that had not previously been considered." (PMID 19232126, 2009).
developmental and epileptic encephalopathy (6 papers, 2023 to 2026). An epilepsy associated with developmental impairment that may be due to either the underlying etiology or the superimposed epileptic activity, or both. "Pathogenic variants in HCN1 are an established cause of developmental and epileptic encephalopathy (DEE)." (PMID 37265603, 2023). "PCDH19, PLCB1, SCN8A, and HCN1 variations were found in Late Infantile Developmental and Epileptic Encephalopathy (LIDEE) patients." (PMID 41153369, 2025). "It was therefore presumed that pathogenic HCN1 variants could produce pharmacoresponsive epilepsy or developmental and epileptic encephalopathy (DEE)." (PMID 37353494, 2023). "De novo missense variants in HCN1 were first reported in 2014 as a cause of early infantile epileptic encephalopathy (EIEE)/developmental and epileptic encephalopathy (DEE), characterized by infantile onset, frequent drug resistance, and fever/heat sensitivity." (PMID 41603014, 2026). "Variants in HCN1 and TMEM63B have been linked to developmental and epileptic encephalopathy (DEE)." (PMID 40167904, 2025).
absence seizures (5 papers, 2012 to 2024). "Moreover, the loss of HCN1 in HCN1-knockout rats caused spontaneous bilateral SWDs accompanied by behavioural arrest, both of which were suppressed by the anti-absence drug ethosuximide, indicating a causal relationship between HCN1 and absence seizures." (PMID 36766503, 2023). "Of interest, increased expression of HCN1 in the somatosensory cortex associated with reduced absence seizures can be produced not only by maternal methyl-enriched diet but also by other early-life environmental impacts such as neonatal handling and maternal separation." (PMID 36766503, 2023). "The HCN1-knockout rat model of the absence seizures reveals a reduction of Ih current in the cortical and hippocampal pyramidal neurons, pronounced hyperpolarizing shift of the resting membrane potential, and increased input resistance." (PMID 35663267, 2022). "Thus, loss of function of dendritic HCN1 channels in layer 5 pyramidal neurons provides a somatodendritic mechanism for increasing the synchronization of cortical output, and is therefore likely to play an important role in the generation of SWDs accompanying absence seizures." (PMID 23738145, 2013). "Given that HCN1-/- mice show enhanced seizure susceptibility and that HCN2-/- mice suffer from absence seizures, we next focused our investigations on the alteration of Ih currents associated with HCN channels in EC layer II in X11-/-/X11L-/- mice." (PMID 23034178, 2012). "Moreover, kainic acid-induced seizure susceptibility is increased in HCN1-/- mice, and HCN2-deficient mice exhibit spontaneous absence seizures." (PMID 23034178, 2012).
Alzheimer disease (5 papers, 2015 to 2024). A progressive, neurodegenerative disease characterized by loss of function and death of nerve cells in several areas of the brain leading to loss of cognitive function such as memory and language. "Many reports have linked HCN1 dysregulation to the etiology of Alzheimer’s disease by affecting neuronal excitability and regulating Aβ generation." (PMID 37292694, 2023). "This specific study suggests that the increased susceptibility to epileptic seizures in Alzheimer’s disease patients may be due to the downregulated HCN1 channels." (PMID 38562955, 2024). "In both aged macaques and in humans with Alzheimer’s disease, amounts of HCN1 channels were found to be lowered in the temporal lobe." (PMID 38562955, 2024). "C-Met, NPTX2, NEUROD6, and hyperpolarization-activated cyclic nucleotide-gated potassium channel 1 have all been found to be HCN1 in a study comparing gene expression in Alzheimer's and nondisordered Alzheimer's diseases." (PMID 35310907, 2022).
idiopathic generalized epilepsy (5 papers, 2015 to 2023). A generalised epilepsy that encompasses several common seizure phenotypes including childhood absence epilepsy, juvenile absence epilepsy, juvenile myoclonic epilepsy and epilepsy with generalized tonic-clonic seizures alone. "Similar to HCN1, some of variants are related to different epileptic syndromes; p.S632W and delPPP (p.719–721) are each related to both febrile seizures and genetic or idiopathic generalized epilepsy." (PMID 35663267, 2022). "This assumption may indeed apply since early infantile epileptic syndromes and idiopathic generalized epilepsy has been associated with mutations in HCN1 and HCN2 channel genes." (PMID 26578877, 2015). "For the HCN1 gene, majority of the cases can present with either febrile seizures, or febrile seizure plus or genetic generalized epilepsy with febrile seizure plus or genetic/idiopathic generalized epilepsy." (PMID 35663267, 2022).
status epilepticus (5 papers, 2022 to 2026). Status epilepticus is defined as a continuous seizure lasting more than 30 min, or two or more seizures without full recovery of consciousness between any of them. "The loss of Ih current and HCN1 channel expression starts 1 h after status epilepticus: it involves several steps, including dendritic HCN1 channel internalization, deferred loss of protein expression, and the final downregulation of mRNA expression." (PMID 35663267, 2022). "The loss of Ih current and HCN1channel expression starts 1 h after status epilepticus and involves several steps, including dendritic HCN1 channel internalization, deferred loss of protein expression, and finally the downregulation of mRNA expression." (PMID 35663267, 2022). "Loss Ih current and HCN1channel expression start 1 h after status epilepticus and involves several steps including dendritic HCN1 channel internalization, deferred loss of protein expression, and finally the downregulation of mRNA expression." (PMID 35663267, 2022). "Both acute and chronic HCN1 downregulation was observed in the hippocampus of a rat model of status epilepticus, leading to the speculation that dysregulation of HCN1 contributes to this condition." (PMID 35679272, 2022).
temporal lobe epilepsy (4 papers, 2012 to 2023). A localization-related (focal) form of epilepsy characterized by recurrent seizures that arise from foci within the temporal lobe, most commonly from its mesial aspect. "The disruption of Ih current disturbs hippocampal theta function in rat models of temporal lobe epilepsy, and during seizures, there is a reduced expression of HCN1 channel and upregulation of HCN2 channel." (PMID 35663267, 2022). "The downregulation of HCN1 expression after seizures augments dendritic excitability, resulting in the development of temporal lobe epilepsy." (PMID 35663267, 2022). "The loss of HCN1 in distal dendrites minimizes the interaction between TRIP8b and HCN1 channels in animal models of temporal lobe epilepsy, which implies that TRIP8b interaction with HCN1 is important for appropriate HCN1 channel function in CA1 pyramidal neuron dendrites." (PMID 35663267, 2022). "For example, HCN1 expression is significantly reduced in the EC after temporal lobe epilepsy." (PMID 23034178, 2012). "This assumption is supported by the fact that HCN1 channelopathy derives from NRSF-mediated transcriptional repression contributing to epileptogenesis, as was shown in a mouse model of temporal lobe epilepsy." (PMID 36766503, 2023). "Several phosphosites for HCN1 and HCN2 have been mapped in chronic epilepsy cases and animal models of temporal lobe epilepsy." (PMID 35663267, 2022).
Dravet syndrome (3 papers, 2016 to 2024).
epilepsy syndrome (3 papers, 2022). A syndrome that has a characteristic cluster of clinical features and/or lectroencephalographic (EEG) findings that reflect underlying epileptic activity. "Similar to HCN1 gene, some of the variants are related to different epileptic syndromes which suggest heterogeneity of the HCN2 phenotypes." (PMID 35663267, 2022). "Some of the variants are related to different epileptic syndromes, which suggest heterogeneity of the HCN1 phenotypes." (PMID 35663267, 2022). "HCN1 pathogenic variants are related to several types of epileptic syndromes." (PMID 35663267, 2022).
post-traumatic stress disorder (3 papers, 2020 to 2025). An anxiety disorder precipitated by an experience of intense fear or horror while exposed to a traumatic (especially life-threatening) event. "In addition, our findings incorporated some significant genes linked to ASD symptoms identified in previous studies, including WDR27 in Cluster 8, previously associated with sleep disturbance, and HCN1 in Cluster 19, previously associated with post-traumatic stress disorder." (PMID 40440618, 2025). "The function of the hyperpolarization-activated cyclic nucleotide-gated channel 1 (HCN1) and the expression of brain-derived neurotrophic factor (BDNF) may be involved in the pathogenesis of post-traumatic stress disorder (PTSD)." (PMID 32198387, 2020).
cognitive decline (2 papers, 2019 to 2024). "In parallel, western blots of the hippocampus of presymptomatic mice (4 months old) were probed with antibodies to HCN1, HCN2, and HCN3 to monitor whether changes in the expression of HCN channels occur before overt cognitive decline in Tau35 mice." (PMID 38994745, 2024).
colorectal cancer (2 papers, 2022 to 2023). A primary or metastatic malignant neoplasm that affects the colon or rectum. "HCN1, coding for hyperpolarization-activated cyclic nucleotide-gated channel subunits, is associated with low survival rates in breast, brain, and colorectal cancer." (PMID 35202405, 2022).
deafness (2 papers, 2023). An inherited or acquired condition characterized by the complete loss of the ability to hear from one or both ears. "However, there are no reports to date of HCN1 loss-of-function variants in humans associated with deafness." (PMID 36689403, 2023).
dementia (2 papers, 2022 to 2024). Loss of intellectual abilities interfering with an individual's social and occupational functions. "In particular, HCN1 has been shown to mis‐localize and become dysfunctional in models of dementia." (PMID 38994745, 2024). "Induced dementia was confirmed by behavioural tests, inflammatory cytokines and oxidative stress tests and histopathological signs of neurodegeneration, multifocal deposition of congo red stained amyloid beta plaques and the decreased optical density of HCN1 immunoreactivity." (PMID 36216854, 2022). "Furthermore, Iva has a potential neurosupportive therapeutic value for the treatment of insulted neurons in dementia and could be a candidate for a new medication to relieve cognitive dysfunctions which might be partly attributed to blocking of HCN1 channels." (PMID 36216854, 2022).
Dependence (2 papers, 2018 to 2020). "It is possible that in mPFC HCN1 deletion mice, increasing the negative consequences associated with alcohol consumption or measuring alcohol consumption after inducing dependence would have more sensitivity in identifying a the role for mPFC HCN1 channels in alcohol consumption." (PMID 33105624, 2020).
developmental delay (2 papers, 2022). "Here we describe the novel HCN1 E246A pathogenic variant, associated with well controlled focal epilepsy, mild developmental delay and parental report of visual dysfunction, that results in a net gain of channel function." (PMID 35359652, 2022). "Although much focus has been on the epileptology and developmental delay of HCN1 disease, there may be pathology in other organs in which HCN1 channels play a role." (PMID 35359652, 2022).
genetic generalized epilepsies (2 papers, 2022 to 2024). "HCN1 p.L157V and HCN4 p.R550C were associated with genetic generalized epilepsy." (PMID 35663267, 2022).
heart failure (2 papers, 2015 to 2023). Inability of the heart to pump blood at an adequate rate to meet tissue metabolic requirements. "mRNAs for ANP, CLCN2 and Navβ1 were increased with heart failure in all regions, while mRNAs for Cx43 and HCN1 were decreased." (PMID 26509807, 2015). "Heart failure in the rabbit leads to prolongation of the PR interval and this is accompanied by downregulation of HCN1, Cav1.3, Cx40 and Cx43 mRNAs and anatomical enlargement of the entire heart and AVJ." (PMID 26509807, 2015). "HCN1 showed an overall significant downregulation in heart failure animals (2-way ANOVA, P = 0.001), while HCN4 was upregulated in the left ventricular septum (Limma test, P = 003)." (PMID 26509807, 2015).
memory impairment (2 papers, 2019 to 2025). "This was supported by studies investigating Scn1a mutant mice and in HCN1 (R43Q) mutants where prior induction of seizures before cognitive testing led to significant memory impairments." (PMID 41585885, 2025).
neuropathy (2 papers, 2017 to 2020). A disorder affecting the nervous system that manifests with pain, tingling, numbness, and/or muscle weakness. "In the current study, we used a neuropathy rat model induced by chronic constriction injury (CCI) of sciatic nerve to evaluate the change of expression of HCN1/HCN2 mRNA in peripheral nerve and spinal cord." (PMID 27901476, 2017). "We explore whether PEMF have a therapeutic effect in CCI induced neuropathy and whether there is a change in the expression of HCN1/HCN2 after PEMF therapy." (PMID 27901476, 2017). "An Hcn1 knockout study conducted by the McNaughton group demonstrated that HCN1, which was mainly expressed in large-diameter neurons, was activated by PGE2-produced cAMP, and that this mechanism was at least partly responsible for cold allodynia caused by pSNL neuropathy." (PMID 31969159, 2020). "Our study revealed the change of expression of HCN1/HCN2 mRNA in the left/right sciatic nerve, left/right dorsal root ganglion (DRG) and spinal cord after CCI induced neuropathy." (PMID 27901476, 2017). "In the left sciatic nerve where neuropathy was induced by CCI, the expression of HCN1/HCN2 mRNA decreased." (PMID 27901476, 2017). "In other regions (LD: left dorsal root ganglion, SP: spinal cord, RD: right dorsal root ganglion, RN: right sciatic nerve) of nerves where no neuropathy was induced, no change of HCN1/HCN2 mRNA was observed." (PMID 27901476, 2017).
Tremor (2 papers, 2015 to 2021). An unintentional, oscillating to-and-fro muscle movement about a joint axis. "A missense mutation (A354V) in the Hcn1 gene was associated with tremor expression in our rat model." (PMID 25970616, 2015).
-linked syndromes (1 paper, 2022). "Moreover, similar to other ion channel-linked syndromes, a variety of disease phenotypes are observed in patients carrying HCN1 pathogenic variants, with DEEs seen in ~20% of cases." (PMID 35972069, 2022).
amyotrophic lateral sclerosis 8 (1 paper, 2018). "Here we show that vesicle-associated membrane protein–associated protein B (VAPB), previously associated with a familial form of amyotrophic lateral sclerosis 8, is an essential HCN1 and HCN2 modulator." (PMID 29879376, 2018).